EGFR (epidermal growth factor receptor)
Diseases named in the same sentence as EGFR in open-access papers (continued):
Sharing a sentence is not in itself a finding about the gene and the disease.
lung cancer (continued). "Our previous study showed that the dysregulated TCA cycle in mitochondria linked the pseudohypoxia signaling pathway to the drug-tolerant persister (DTP) state acquisition in EGFR-mutant lung cancer." (PMID 35840668, 2022). "NF-­κB activation is rapidly induced in response to EGFR oncogene inhibition in lung cancer and promotes resistance to therapy via interleukin 6 (IL­-6) induction." (PMID 35399416, 2022). "In this study, aged patients with lung cancer showed some specific gene alterations, such as a relative high proportion KRAS codon 61 in the KRAS mutated patients, and the various mechanism of EGFR TKIs resistance." (PMID 35031014, 2022). "Significant inverse associations were also observed among EGFR+ (OR = 077, 95% CI = 0.61–0.96) and EGFR- lung cancer (OR = 0.72, 95% CI = 0.55–0.94)." (PMID 36530673, 2022). "For example, in gastric and lung cancers, cancer cells induce anoikis resistance and metastasis through epidermal growth factor receptor (EGFR) signaling." (PMID 36249029, 2022). "EGFR testing is recommended for all patients with lung cancer in advanced stages (stages 3b, 3c, and 4) of adenocarcinoma, especially in females and nonsmokers." (PMID 36233811, 2022). "In contrast, the Japanese Lung Cancer Society states that plasma testing should only be performed when it is difficult to perform EGFR gene testing on lung cancer tissue specimens for medical reasons." (PMID 36192767, 2022). "Coincidentally, Han W and other studies have shown that EGFR-TKIs, such as gefitinib and erlotinib, can activate autophagy of human lung cancer cells, and then the growth inhibitory effect of EGFR-TKIs on cancer cells is weakened." (PMID 35600411, 2022). "In particular, the L-scores of lung cancer cell lines were negatively correlated with their sensitivity to EGFR inhibitors." (PMID 35016696, 2022). "There is limited knowledge regarding the gastrointestinal microbiota profile of patients with advanced EGFR-WT and EGFR-mutant lung cancer who received chemotherapy and targeted therapy." (PMID 36076157, 2022). "Patients with EGFR-positive lung cancer are expected to respond to EGFR-TKI therapy, although almost all develop resistance 1–2 years after starting treatment." (PMID 34643820, 2022). "Targeted drugs against KRAS-, EGFR- or ALK-driven lung cancer induce apoptosis and pyroptosis simultaneously." (PMID 36411454, 2022). "Analysis of blood samples from metastatic colorectal cancer patients, as well as lung cancer patients, demonstrated that increased EpCAM+EGFR+ events were detected in more than half of the patient samples." (PMID 36613466, 2022). "Unfortunately, the median progression-free survival of patients with EGFR-mutant lung cancer treated with TKI is 8 to 13 months." (PMID 35027025, 2022). "Accumulating evidence has indicated that ncRNAs, especially circRNAs, lncRNAs and miRNAs, play a vital role in EGFR TKI-resistant lung cancer via alternative signaling pathway modulation." (PMID 36139582, 2022). "This study aims to reveal the role of glucagon-like peptide (GLP) 2 and GLP-2 receptor (GLP2R) signaling on the EGFR-TKIs and cisplatin resistance of lung cancer cells." (PMID 35027025, 2022). "EGFR signaling pathway is involved in the regulation of lung cancer cell proliferation, migration, invasion, apoptosis, and other biological processes." (PMID 35090513, 2022). "Recently, it has been reported that the transformation of EGFR-mutant lung cancer from adenocarcinoma to small-cell lung cancer at the time of acquired resistance is associated with the appearance of APOBEC mutational signatures." (PMID 35402275, 2022). "A similar trend was observed in both EGFR + lung cancer and EGFR–lung cancer, however, the high consumption of total vegetables was statistically significant only among EGFR+ lung cancer (OR = 0.69, 95% CI = 0.54–0.88)." (PMID 36530673, 2022).
lung cancer (continued). "In that study, most of the patients had advanced lung cancer (70.6%), and serum EGFR mRNA expression was considered a marker for predicting treatment response and survival outcomes in non-small-cell carcinoma." (PMID 35053080, 2022). "Remarkably, miR-19b interacts with PP2A and BIM to simultaneously promote the phosphorylation of AKT, ERK and STAT, indicating its potential as a promising therapeutic target for affecting multiple pathways of EGFR TKI-resistant lung cancer." (PMID 36139582, 2022). "In a similar fashion, it has been suggested that the intercellular transfer of exosomal wild-type epidermal growth factor receptor (EGFR) into lung cancer cells is mediated by clathrin endocytosis." (PMID 35563681, 2022). "With the understanding of biomarkers for lung cancer, biomarker studies including EGFR expression are strongly recommended in advanced NSCLC, but not in all stages." (PMID 36079152, 2022). "In stage 3 and 4 patients with EGFR mutations, the LCF group showed better survival than the single lung cancer group." (PMID 36233811, 2022). "The remarkable advent of gefitinib in 2000, EGFR tyrosine kinase inhibitor (EGFR-TKI) targeted therapy as a representative precision medicine has facilitated spectacular alterations to the lung cancer study philosophy and treatment model." (PMID 35606799, 2022). "In lung cancer, they are used to treat advanced EGFR-mutant diseases, and more recently, one has been approved for adjuvant therapy." (PMID 35565386, 2022). "Activating EGFR mutations are the known drivers of lung cancer that accounts for approximately 10 to 15% of non-small cell lung cancer (NSCLC) diagnoses and assessment of EGFR mutations is now routinely performed as standard of care." (PMID 35209919, 2022). "Preclinical studies have shown that immune cell function in EGFR-mutant lung cancer is restored after EGFR-TKI treatment." (PMID 36612121, 2022). "Epidermal growth factor receptor (EGFR) is a key protein that plays crucial roles for tumorigenesis and cancer therapy of lung cancers." (PMID 36678740, 2022). "In a study of 11 patients with EGFR-expressing advanced (>50% expression) relapsed/refractory nonsmall-cell lung cancer who received the EGFR-targeted CAR-T cells treatment, only 2 patients obtained partial responses." (PMID 36389701, 2022). "Our previous study has found that cell-penetrable nanobodies targeted at EGFR-tyrosine kinase were significantly reduced EGFR-positive lung cancer cells viability and proliferation." (PMID 35578244, 2022). "EGFR inhibitors are important targeted drugs for the treatment of lung cancer, which can significantly improve the prognosis of patients." (PMID 36176446, 2022). "Another example of this is the use of an EGFR-induced lung cancer Drosophila model to identify an alternative combinational therapy for lung cancer patients." (PMID 36003330, 2022). "In fact, compared with other targeted therapies (e.g. ALK-TKI and VEGFR), EFGR-TKI treatments result in more severe skin ADRs, which is especially true for lung cancer treatment, in which EGFR-TKIs have been commonly used." (PMID 35505288, 2022). "Germline mutations resulted in lung cancer pathogenesis by the constitutive activation of proto-oncogenes, such as the members of the EGFR (ERBB), MYC, and RASfamilies, PIK3CA, NKX2-1, and ALK." (PMID 36277983, 2022). "The idea of combining EGFR inhibition with FAK inhibition for therapeutic purposes in lung cancer has been tested previously." (PMID 35884490, 2022). "EGCG inhibited the proliferation of human lung cancer cells through targeting the epidermal growth factor receptor (EGFR) signaling pathway." (PMID 36545470, 2022). "Although EGFR-TKI is very effective in the treatment of EGFR mutant lung cancer, resistance to these agents develops within an average of about 1 year." (PMID 35190747, 2022). "Overcoming resistance to EGFR-TKIs is essential if we are to develop better therapeutic strategies for lung cancer patients." (PMID 35740609, 2022).
lung cancer (continued). "In our results, lung cancer patients showed higher APOBEC signature in baseline compared with resistance to the EGFR-TKI group." (PMID 35402275, 2022). "Stc2/Jun/Axl signal activation can mediate the acquired resistance of lung cancer patients to EGFR tyrosine kinase inhibitors." (PMID 35634481, 2022). "Lung cancer, especially NSCLC, remains the leading cause of cancer death, and osimertinib is an important first-line drug for EGFR mutation-positive NSCLC." (PMID 35168607, 2022). "The studies show that RA promotes the synthesis of EGFR in human lung cancer cells, which is reflected by their rising tumorigenicity phenotype." (PMID 35631448, 2022). "For example, in the EORTC APPLE trial (NCT 02856893), patients with EGFR mutant lung cancer are randomised to receive either gefitinib followed by osimertinib based on progression detected by plasma ctDNA or detected by standard imaging." (PMID 35347327, 2022). "The results of our array analysis suggest that many different cytokines are elevated during the coculture of EGFR-mutant lung cancer cells and activated PBMCs." (PMID 36612121, 2022). "Many cancer biomarkers have been elucidated, such as KRAS in colorectal cancer, human epidermal factor receptor 2(HER2) in breast cancer, and EGFR in lung cancer." (PMID 36589754, 2022). "Resistance to EGFR tyrosine kinase inhibitors (TKIs) is one of the major obstacles in lung cancer therapy." (PMID 35053430, 2022). "Given the role of EGFR in lung cancer, we explored TCGA data which revealed that a subset of PTPRH mutant tumors shared gene expression profiles with EGFR mutant tumors, but that EGFR mutations and PTPRH mutations were mutually exclusive." (PMID 36054194, 2022). "Alterations in the pocket protein pathway identify EGFR mutant lung cancer patients that have worse outcomes on this therapy." (PMID 35368709, 2022). "Pelitinib is a powerful irreversible epidermal growth factor receptor (EGFR) tyrosine kinase inhibitor studied in clinical studies to treat lung cancer." (PMID 35453310, 2022). "Recent studies have also demonstrated improved disease-free survival with adjuvant osimertinib in those with resected EGFR mutant lung cancer, and adjuvant atezolizumab in those with resected stage II-III PD-L1-positive NSCLC." (PMID 35347327, 2022). "Studies on lung adenocarcinoma have shown that the EGFR ligand is rapidly released to activate the EGFR and mitogen-activated protein kinase signaling pathways when lung cancer cells are stimulated with estrogen." (PMID 35854298, 2022). "A future study adopting a rational trial design and advanced technologies to explore the ncRNAs involved in EGFR TKI-resistant lung cancer would overcome barriers that hinder mechanistic investigation and clinical application." (PMID 36139582, 2022). "RTKs such as EGFR, the classical driver of lung cancer, are important components of the cellular signaling apparatus and are frequently mutated or otherwise dysregulated in NSCLC." (PMID 38091511, 2022). "Among the molecular alterations predicting response to targeted treatment in lung cancer, epidermal growth factor receptor (EGFR) inhibition was the first to succeed." (PMID 36012655, 2022). "Treatment with the BR2-2xPPD peptide enhanced cytotoxic effects in acquired EGFR-TKI resistant lung cancer cells." (PMID 35235599, 2022). "As observed in lung cancer, dysregulation of the EGFR pathway results in upregulation of the human vascular endothelial growth factor (VEGF) pathway." (PMID 35626731, 2022). "Together, this study demonstrates that ND-conjugated Cet can apply for targeting EGFR and monitoring tumorigenesis during lung cancer progression and therapy." (PMID 36678740, 2022). "Strategies for lung cancer patients with KRAS mutations and EGFR-TKI resistance are limited, and it is imperative to develop new EGFR-TKI sensitizers and combination strategies to overcome resistance to EGFR-TKIs." (PMID 36712673, 2022).
lung cancer (continued). "It has been noted that in many cases, resistance takes the form of the cancer cells losing the EGFR-mut and becoming like EGFR-WT lung cancers." (PMID 35061724, 2022). "Recently, CXCL10 levels were found to be elevated in EGFR-mutant lung cancer immediately after EGFR-TKI treatment." (PMID 36612121, 2022). "A previous study in 36,813 Chinese lung cancer patients, focusing on eight key lung cancer driver genes (EGFR, ALK, MET, KRAS, ERBB2, ROS1, RET, and BRAF), revealed a prevalence of 0.03% for P/LP germline mutations." (PMID 35428225, 2022). "Among 80 patients with EGFR-mutant lung cancer, 42 received ICI monotherapy and 38 received chemoimmunotherapy." (PMID 36082280, 2022). "In this study, we discovered for the first time that dysregulated purine metabolism contributes to the acquisition of the DTP state, regulated by the miR-21 guide and passenger strand repressing ADSL in EGFR-mutant lung cancer cells." (PMID 35840668, 2022). "In this manner, miR-21 in lung cancer treated with EGFR TKIs is inversely upregulated and thus stimulates the TNF/NF-κB pathway, which consequently causes EGFR TKI resistance in lung cancer." (PMID 36139582, 2022). "By manipulating magnetic albumin nanospheres, the MAIN significantly increased the adhesion and absorption of GLC-82 lung cancer cells overexpressing EGFR (MANs)." (PMID 36085575, 2022). "Combination treatment with MA and osimertinib improved the sensitivity of lung cancer cells to EGFR-TKIs through ROS suppression of the KRAS-ERK signaling pathway, as well as NRF2-SLC7A11 axis inhibition- and mitochondrial Ca2+ overload-triggered ferroptosis." (PMID 36712673, 2022). "The prevalence of driver oncogenic alterations in patients with lung cancer, particularly EGFR, BRAF, HER2 and ROS1, was significantly higher in high exposure areas." (PMID 36208308, 2022). "In contrast, many miRNAs, such as miR-133a-3p, are regulates drug resistance in lung cancer patients by working with EGFR signaling networks." (PMID 36386184, 2022). "Analogous results were found by previous research demonstrating that TMB was negatively associated with clinical outcomes in metastatic patients with EGFR-mutant lung cancer treated with first- or second- generation EGFR TKIs." (PMID 35643428, 2022). "EGFR mutant lung cancer cells evade Gefitinib therapy by over-activating STAT3 via miR-206 down regulation." (PMID 35264191, 2022). "In an analysis of survival rates among lung cancer patients, the higher the expression of Ephexin1, EGFR, EphA1, and EphA2, the lower the rate." (PMID 35668076, 2022). "This review appraises current literature, opportunities, and challenges associated with liquid biopsy and pharmacogenomic (PGx) testing as precision therapy tools in the management of EGFR mutant and resistant lung cancers." (PMID 35209919, 2022). "In EGFR-mutant lung cancer, drug-tolerant persister cells (DTPCs) show prolonged survival when receiving EGFR tyrosine kinase inhibitor (TKI) treatments." (PMID 35840668, 2022). "We will also continue to monitor the impact of the miR-199a/Rheb/mTOR axis on the development of resistance to the treatment of tumors in lung cancer, especially about EGFR-TKIs resistance." (PMID 35844793, 2022). "A frequently altered cell signalling pathway in both breast and lung cancer is the Human Epidermal growth factor Receptor (HER) pathway." (PMID 35326716, 2022). "According to some findings, LXR agonist T0901317 was shown to render natural EGFR-TKI-resistant A549 human lung cancer cells in response to EGFR-TKI treatment which is LXRβ-dependent." (PMID 35631448, 2022). "For instance, mAbs targeting Epidermal Growth Factor Receptor (EGFR) or Human Epidermal Growth Factor Receptor 2 (HER2) have dramatically improved the survival outcomes of patients affected by lung cancer, breast cancer and other solid malignancies." (PMID 36432631, 2022).
lung cancer (continued). "Examples of this are the small molecule EGFR tyrosine kinase inhibitors, which enhance survival in lung cancer but are ineffective in glioblastoma, even though EGFR is amplified and mutated to a constitutively active form in many glioblastomas." (PMID 33753869, 2022). "LncRNAs could serve as potential predictive and prognosis markers for EGFR resistant and mutant lung cancers as, they have been implicated in the regulation of chemosensitivity, radiosensitivity, and sensitivity of EGFR targeted therapies in lung cancers through diverse mechanisms." (PMID 35209919, 2022). "Given the importance of EGFR activity in lung cancer, we confirmed the causal nature of PTPRH loss on EGFR activity through CRISPR mediated knockout of PPTPRH in a NSCLC line by observing increased pEGFR and pAKT." (PMID 36054194, 2022). "Treatment with BB1608, a STAT3 inhibitor, results in decreased G9a and HER3 expression and sensitizes lung cancer cells to EGFR tyrosine kinase inhibitor." (PMID 35740522, 2022). "Carfilzomib treatment increased infiltration of anti‐tumor inflammatory macrophages and CD8+ T cells in tumor loci and partially shrank mutant EGFR‐driven lung cancers." (PMID 34898004, 2022). "We suggest that ND-Cet enhances the uptake ability through the binding of EGFR in patient lung cancer cells." (PMID 36678740, 2022). "In stage 3 and 4 patients with EGFR mutation and undetected EGFR, survival in the LCF group was better than that in the single lung cancer group." (PMID 36233811, 2022). "In particular, the third-generation EGFR-TKI, Osimertinib, the first-line TKI of choice for EGFR-mutant lung cancer with BMs, was demonstrated to be more efficient." (PMID 36354720, 2022). "Our study found that Proteobacteria was the most abundant phylum in Thai lung cancer patients, whereas the abundance of Actinobacteria was diminished in both the EGFR-WT and EGFR-mutant cohorts." (PMID 36076157, 2022). "Mechanisms of acquired resistance to EGFR inhibitors in EGFR mutant lung cancer are diverse and include genomic mechanisms such as point mutations, amplifications, and oncogenic fusions." (PMID 36153311, 2022). "In multiple lung cancer cell lines, EGFR signaling effectively reduced the levels of TNF-α, and the inhibition of EGFR resulted in the increased levels of TNF-α through the alteration of mRNA stability." (PMID 36204127, 2022). "An association between ALDH1A1 and EGFR TKI resistance in lung CSCs has been investigated, wherein ALDH1A1+ lung cancer cells were found more resistant to gefitinib than the corresponding ALDH1A1− fraction." (PMID 35053430, 2022). "Epidermal growth factor receptor (EGFR)-mutant nonsmall cell lung cancer (NSCLC) patients are less likely to be programmed death-ligand 1 (PD-L1)-positive compared with wild-type EGFR mutant tumors." (PMID 35984168, 2022). "Given the limitations of previous reports, this study further described the role of CAFs in lung cancer EGFR TKIs resistance development." (PMID 35831824, 2022). "•Concomitant EGFR sensitizing mutation and MET overexpression/amplification were detected in 2.6% of lung cancer patients." (PMID 34953403, 2022). "In the HER2/neu‐inducible breast cancer mouse model, recurrent tumors displayed an EMT signature and an EMT shift has been observed in a portion of lung cancer patient samples that acquired resistance to EGFR inhibitors." (PMID 35398967, 2022).